ENSG00000285646 (novel transcript)
Gene: Long non-coding RNA gene on chromosome 1 (11,907,940 to 11,925,009, forward strand). Ensembl gene ENSG00000285646.
Gene Ontology:
Biological process: formation of quadruple SL/U4/U5/U6 snRNP; spliceosomal tri-snRNP complex assembly
Cellular component: U4/U6 x U5 tri-snRNP complex; U5 snRNP